PDPN (podoplanin)
Diseases named in the same sentence as PDPN in open-access papers (continued):
Sharing a sentence is not in itself a finding about the gene and the disease.
glioma (continued). "We observed that PDPN-deficient macrophages show a significantly impaired transcriptional upregulation of Arg1 expression in response to three different glioma cell lines." (PMID 30972297, 2019). "PTX3, FAPB7, POSTN, and PDPN are associated with increased glioma invasion, and both PDPN and CHI3L1 reportedly contribute to radio-resistance in glioblastoma." (PMID 29523123, 2018). "In a prospective cohort study, intratumoral IDH1 R132H mutation and podoplanin were determined in brain tumor specimens (mainly glioma) by immunohistochemistry." (PMID 29676036, 2018). "Interestingly, PDPN is associated with the progression and invasion of various cancers, including gliomas." (PMID 40554484, 2025). "By processing data from the TCGA and TCIA databases for statistical and imaging histological analysis, high PDPN expression was significantly associated with poor prognosis in patients with high-grade glioma through survival analysis as well as univariate and multivariate regression analyses." (PMID 40554484, 2025). "Prior studies have suggested that IDH status may regulate PDPN expression in gliomas, and that IDH mutation stratification is clinically significant." (PMID 40554484, 2025). "PDPN expression is strongly associated with a poor prognosis in gliomas." (PMID 40554484, 2025). "The findings revealed an association of PDPN with macrophage M2-like polarization in glioma." (PMID 39682237, 2024). "When we compared IDH mutation status (a prognostic factor that correlates with better survival), we found that expression levels of PDPN are overall lower in grade I/II IDH-mutated glioma and are elevated in grade IV IDH-mutated specimens (IDH mutant, n=37; IDH wild-type, n=224; p<0.0001)." (PMID 36059614, 2022). "Thus, in this study we examined tumor-associated PDPN+ myeloid cells and their effect on glioma development and immune cell infiltration." (PMID 30972297, 2019). "PDPN is used as a molecular marker for glioma, due to its association with clinical outcomes." (PMID 23717195, 2013). "Mechanistically, podoplanin (PDPN) expressed on glioma cells directly engages CLEC5A and triggers downstream Syk-JAK-STAT3 signaling in TAMs." (PMID 42228429, 2026). "A total of 298 high-grade glioma samples from the TCGA database meeting the study criteria were categorized into two groups based on PDPN expression levels: high and low." (PMID 40554484, 2025). "In glioma cells, the knockdown of PDPN leads to decreased proliferation, 2D migration, and invasion of collagen." (PMID 40554484, 2025). "PDPN has been reported to identify “a subset of aggressive and radiation-resistant glioblastoma cells” and predict “poor prognosis in patients with glioma” and that it “contributes to constructing immunosuppressive microenvironment in IDH wildtype glioma”." (PMID 39941811, 2025). "Analysis of high-grade glioma samples from TCGA and normal tissue samples from GTEx indicated that PDPN was significantly higher in high-grade glioma tissue compared to normal tissues (p < 0.001)." (PMID 40554484, 2025). "Higher PDPN protein expression was observed in high-grade gliomas compared to low-grade gliomas, as shown in immunohistochemistry images downloaded from the HPA database." (PMID 38504986, 2024). "In primary human glioblastoma and glioma cell lines, there is an inverse relationship between the levels of PDPN and phosphatase and tensin homolog (PTEN)." (PMID 40741180, 2024). "They performed multiplexed fluorescence immunohistochemistry staining of several markers in glioma tissue microarrays to investigate the impact of a specific marker, PDPN, on macrophages’ immunosuppressive polarization using a co-culture system." (PMID 39682237, 2024). "We further explored the expression pattern of PDPN in patients with gliomas and its relationship with prognosis in TCGA." (PMID 38470096, 2024).
glioma (continued). "Of the 11 candidate susceptibility regions, two regions were consistently associated with glioma risk across multiple studies and methods, 16p13.3 an intronic region of the RBFOX1 gene, and 1p36.21 containing the genes PDPN and PRDM2." (PMID 39387520, 2024). "Bulk RNA‐seq and single‐cell RNA‐seq of glioma patients from public databases were comprehensively analyzed to illustrate macrophage infiltration patterns and molecular characteristics of podoplanin (PDPN)." (PMID 38470096, 2024). "Recent studies have revealed that PDPN is upregulated in various cancers, especially high in tumors derived from immune‐privileged organs, such as glioma and testis cancer." (PMID 38470096, 2024). "Glioma cells release PDPN and/or tissue factors (TFs) within extracellular vesicles, prompting platelet activation and the clotting cascade." (PMID 39682237, 2024). "Tumors that developed in mice after being injected with PDPN-expressing glioma cells triggered distinct profiles of circulating markers associated with thrombosis." (PMID 40741180, 2024). "Research has shown that PDPN identifies a specific subset of aggressive, treatment-resistant glioma cells that contribute to radiation resistance." (PMID 39682237, 2024). "As a result, PDPN was found to be overexpressed in the majority of glioma tissues compared with normal tissues and was positively correlated with certain prognostic factors such as TERT promoter mutation status and ATRX retention status." (PMID 39682237, 2024). "IDH1 is reported to regulate podoplanin (PDPN) expression in glioma by regulating its promoter methylation status." (PMID 38241355, 2024). "In EGFRvIII (an oncogenic form of epidermal growth factor receptor)-driven glioma cells, the expression of PDPN was found to be under negative regulation by the chromatin modifier enhancer of zeste homolog 2 (EZH2)." (PMID 40741180, 2024). "The result showed that the overall survival (OS) time of glioma patients with higher PDPN expression were shorter than glioma patients with lower PDPN expression in the TCGA RNA-seq database (p < 0.001)." (PMID 36434176, 2023). "Our findings contribute to re-recognizing the role of PDPN in IDH wildtype gliomas and implicate promising target therapy combined with immunotherapy for this highly malignant tumor." (PMID 36434176, 2023). "A correlation between sCLEC-2 levels and PDPN expression was reported in patients with high-grade gliomas." (PMID 38067218, 2023). "Knockdown of PDPN in glioma cells resulted in decreased proliferation, 2D migration, and invasion into a collagen matrix." (PMID 36434176, 2023). "A combination of anti-podoplanin CAR T cells with oncolytic herpes virus G47D successfully reduced ‘on-target off tumor’ toxicity acting against patient-derived glioma stem cells while sparing normal cells." (PMID 36721153, 2023). "To further confirm the expression level of PDPN in gliomas, we took advantage of clinical human glioma samples to determine the relationship between the expression of PDPN in glioma tissues and glioma grades." (PMID 36434176, 2023). "The expression of PDPN was abundant in WHO grade IV glioma tissues and lower expression levels in WHO grade III glioma tissues, especially in the vascular zone." (PMID 36434176, 2023). "Pearson correlation also validated that PDPN was correlated with marker genes of macrophage in gliomas, such as, CD68, etc.." (PMID 36434176, 2023). "In this study, Lp2-CAR-transduced T cells (Lp2-CAR-T) specifically targeted PDPN-expressing glioma cells while sparing the PDPN-expressing normal cells." (PMID 35991754, 2022). "In a study, Lp2 CAR-T cells were designed to target PDPN-expressing glioma cells to exclude normal PDPN-expressing cells." (PMID 36261831, 2022). "To explore the biological role of PDPN, we studied its function in human adherent glioma cell lines and patient-derived glioma-stem-like cultures." (PMID 36059614, 2022).
glioma (continued). "Real-time cell analysis showed that the percentages of lysis of the cancer-type PDPN-expressing glioma cells LN229/hPDPN and LN319 were significantly higher with Lp2-CAR-T cells than with PBMCs." (PMID 35991754, 2022). "It was also suggested that glioma-derived podoplanin and TF coexpressing EVs cooperatively enhance micro-thrombosis in glioma xenograft murine models." (PMID 36013171, 2022). "We further tested the role of PDPN in radioresistance and found that knockdown of PDPN was sufficient to sensitize glioma cell lines to radiation." (PMID 36059614, 2022). "Anti-PDPN mAb NZ-1 conjugated with 131I was first evaluated to be internalized into glioma cells and delivered to malignant glioma-bearing mice." (PMID 35159384, 2022). "We first tested for PDPN expression in multiple adherent human glioma cell lines, using normal human astrocytes (NHA) as a negative control and found that PDPN was highly expressed in U87 and LN319 cells." (PMID 36059614, 2022). "In primary human glioblastoma (GBM) and glioma cell lines, an inverse correlation between PDPN expression and PTEN levels was reported." (PMID 35159384, 2022). "In the present study, we examined PDPN expression across large glioma cohorts in addition to The Cancer Genome Atlas (TCGA) and found PDPN to indeed be an independent prognostic marker among glioma patients." (PMID 36059614, 2022). "In contrast to CD133, PDPN exhibits a more prominent cellular distribution and has a gene expression profile that increases with glioma grade." (PMID 36059614, 2022). "Subcutaneous tumors were established by injecting the mice with PDPN-transfected LN229/hPDPN glioma cells, and treatment was started when the mean tumor diameter reached 5 mm." (PMID 35991754, 2022). "Like GBM, lower-grade glioma patient OS also inversely correlated with PDPN protein expression (p=0.003)." (PMID 36059614, 2022). "In the present study, we demonstrated that PDPN is an independent prognostic marker of patient survival in glioma." (PMID 36059614, 2022). "We explored the prognostic value of PDPN expression across gliomas in TCGA and verified the findings in independent glioma cohorts at both the protein and mRNA levels." (PMID 36059614, 2022). "Recently, new targets of CAR T cells in glioma: podoplanin (PDPN), a member of type I transmembrane glycoproteins, as well as CD70, one of the tumor necrosis factor receptors have been recognized." (PMID 33673696, 2021). "A preliminary study showed radiolabeled NZ-16 highly bound to PDPN-expressing LN-319 glioma cells and showed high tumor uptake." (PMID 34685483, 2021). "To further validate the expression of four genes in gliomas, we next detected their expressions in The Human Protein Atlas database, and the results revealed the PDPN and TIMP1 were higher expression in high-grade gliomas." (PMID 33123464, 2020). "In glioma, PDPN is considered as a novel marker of glioma-dervied cancer stem cells for the low sphere formation rates and resistance to ionizing radiation in the PDPN-positive group." (PMID 32408907, 2020). "In order to investigate the effect of PDPN+ myeloid cells on glioma development, we generated a mouse line that carries a myeloid-specific deletion of Pdpn by crossing a Pdpnflox/flox with a Csf1r-Cre transgenic line." (PMID 30972297, 2019). "To determine the PDPN+ myeloid cell type in gliomas we combined the CD11b and PDPN staining with CD45." (PMID 30972297, 2019). "Systemic infusion of these CAR T cells into immunodeficient mice inhibited the growth of intracranial glioma xenografts in vivo, pointing to podoplanin as a potential target to treat glioblastomas by adoptive immunotherapy." (PMID 30736372, 2019). "Here we show that the deletion of Pdpn in myeloid cells results in increased T-cell infiltrates and significantly prolonged survival, identifying the PDPN+ myeloid cell population as one mediator of the glioma-induced immune suppression." (PMID 30972297, 2019).
glioma (continued). "Immunofluorescence staining and flow cytometry of glioma-bearing mouse brains revealed the presence of a PDPN+ myeloid subpopulation." (PMID 30972297, 2019). "Podoplanin was also proposed as a candidate marker for CSCs in esophageal SCCs and gliomas/glioblastomas." (PMID 30736372, 2019). "In summary, our observation of the prolonged survival of glioma-bearing cKO animals indicates that the PDPN+ myeloid subpopulation promotes glioma progression." (PMID 30972297, 2019). "Similar findings have been observed in patients with glioma in that neurosphere formation and the expression of stem cell markers, such as podoplanin (PDPN), CD133, and nestin, were found to be prognostic markers of clinical outcomes." (PMID 25580136, 2014). "In this study, we assessed the prognostic role of the isolation of glioma CSCs (gCSCs) and expression of stem cell markers (PDPN, CD133, and nestin)." (PMID 25580136, 2014). "Therefore, combining PDPN expression levels in high-grade gliomas with MRI-based radiomics models allowed us to generate additional prognostic information to aid clinical decision-making." (PMID 40554484, 2025). "The clinical prognosis of patients with high-grade glioma was predicted non-invasively in this study by analyzing the expression level of PDPN using an enhanced MRI-based radiomics model, which was constructed using a gradient boosting machine in conjunction with transcriptomics." (PMID 40554484, 2025). "This approach combines PDPN expression levels with radiomics data of high-grade glioma patients, incorporating the gradient boosting machine model into radiomic feature analysis and demonstrating significant correlations with both tumor heterogeneity and PDPN expression levels." (PMID 40554484, 2025). "Additionally, recent studies have highlighted the role of inflammatory and metabolic markers, such as elevated tissue factors and podoplanin levels in IDH wild-type gliomas, in promoting a hypercoagulable state." (PMID 40862818, 2025). "While patients with glioma that harbour a mutation in the isocitrate dehydrogenase (IDH)‐1 gene were found to be at very low risk of VTE,3, 4 intratumoral expression of the sialomucin‐like glycoprotein podoplanin was found as a major risk factor for VTE." (PMID 38613361, 2024). "PDPN is expressed in different types of cancer, including mesothelioma, seminoma, and glioma." (PMID 38890693, 2024). "Notably, PDPN was detected in exosome-like extracellular vesicles released by glioma cells expressing PDPN." (PMID 40741180, 2024). "Additionally, PDPN knockdown was found to suppress proliferation and reduce protein expression in glioma cells." (PMID 39682237, 2024). "Moreover, in the CGGA RNA-seq database (n = 693 and n = 325), glioma patients with higher PDPN expression were also connected with a worse prognosis than those with lower PDPN expression (p < 0.001)." (PMID 36434176, 2023). "In this study, to investigate PDPN potential mechanisms promoting malignancy of glioma, WGCNA was employed to help discover gene functions and identify disease/phenotype-associated genes in glioma based on TCGA database." (PMID 36434176, 2023). "As shown in a mouse model, blocking PDPN specifically on glioblastoma cells could represent a novel strategy to prevent platelet aggregation and, thereby, reduce the risk of VTE in glioma." (PMID 38067218, 2023). "On one hand, given that platelet-derived-growth factor (PDGF) has been reported to promote macrophages survival and polarization, neutrophils activation and secretion, we proposed PDPN can aggregate and activate platelets in glioma, allowing cytokines secretion to form the IME." (PMID 36434176, 2023). "Furthermore, podoplanin derived from glioma cells exacerbates platelet aggregation in tumors in a mouse model." (PMID 37386100, 2023). "PDPN therefore identifies a subset of aggressive, treatment-resistant glioma cells responsible for radiation resistance and may serve as a novel therapeutic target." (PMID 36059614, 2022).
glioma (continued). "Since PDPN expression exhibited a prominent inverse correlation with glioma WHO grade, which are more anaplastic with increasing grade, we suspected that the glycoprotein may be involved with glioma differentiation." (PMID 36059614, 2022). "Knockdown of PDPN radiosensitized glioma cell lines and glioma-stem-like cells (GSCs)." (PMID 36059614, 2022). "In the Vienna Cancer and Thrombosis study it was found that, in high-grade, podoplanin-expressing gliomas, peripheral blood parameters were also significantly affected (lower blood platelet count, higher level of Factor VIII acitivity and higher prothrombin fragment 1 + 2)." (PMID 34200229, 2021). "Additionally, we confirmed that PDPN and TIMP1 were higher expressed in high-grade glioma, and the Pearson correlation validated that PDPN and TIMP1 were correlated with marker gene of macrophage and indicated m6A gene." (PMID 33123464, 2020). "Podoplanin expression is upregulated in a large variety of cancers, including angiosarcomas, chondrosarcomas, osteosarcomas, malignant mesotheliomas, germ-cell tumors, gliomas, glioblastomas, and SCCs." (PMID 30736372, 2019). "Likewise, the conditioned medium obtained from glioma cells overexpressing podoplanin strongly induced angiogenesis in vitro with respect to mock transfected cells." (PMID 30736372, 2019). "Moreover, expression levels of PDPN were significantly correlated with increasing glioma grade, whereas TMEM100 showed the opposite pattern, suggesting that both of these markers are associated with prognosis, even when low-grade glioma samples were included." (PMID 31332251, 2019). "In vitro characterization of PDPN+ and Pdpn knockout macrophages showed PDPN-dependent enhanced Arg1 expression, an enzyme with known pro-tumorigenic function in the tumor microenvironment, in response to the presence of glioma cells." (PMID 30972297, 2019). "This paradigm may lead to novel skin cancer treatments, and pave the way to treat other cancers with elevated PDPN expression levels including breast, glioma, and oral cancer." (PMID 22844530, 2012). "Therefore, PDPN may be a prognostic marker for high-grade gliomas, facilitating early diagnosis and prognosis prediction." (PMID 40554484, 2025). "Additionally, heterogeneous expression of PDPN at different levels within gliomas was observed." (PMID 39682237, 2024). "Furthermore, according to the ROC curve (AUC values = 0.936, 0.978, and 0.896, respectively), PDPN expression might be a robust predictor for WHO grade, IDH mutation and 1p/19q co‐deletion state in gliomas in TCGA dataset." (PMID 38470096, 2024). "Therefore, we speculated that PDPN plays an important role in the construction of glioma immune microenvironment." (PMID 36434176, 2023). "Then multivariate analysis was performed, and it was found that among these factors, PDPN (HR = 1.226; 95% CI = 1.048–1.434; p < 0.05) remained independently related to overall survival, suggesting that PDPN could be an independent prognostic factor for glioma patients." (PMID 36434176, 2023). "Indeed, there are many different cancer-stem-cell niches that exist within the glioma environment (i.e., perivascular, hypoxic, invasive, tumor border, white matter, and necrotic niches), and the role of PDPN and other cellular markers within those niches remains to be defined." (PMID 36059614, 2022). "However, how PDPN regulates macrophage polarization in glioma remains unclear." (PMID 38470096, 2024). "Multiplexed fluorescence immunohistochemistry staining of PDPN, GFAP, CD68, and CD163 were performed in glioma tissue microarray." (PMID 38470096, 2024). "Our findings demonstrated that PDPN is notably correlated with the expression of CD68 and CD163 in glioma tissues." (PMID 38470096, 2024).